TIMP1 (TIMP metallopeptidase inhibitor 1)
Diseases named in the same sentence as TIMP1 in open-access papers (continued):
Sharing a sentence is not in itself a finding about the gene and the disease.
colon carcinoma (continued). "In this study, we constructed a 6-gene signature (ITLN1, HOXD9, TSPAN11, GPRC5B, TIMP1 and CXCL13) prognostic stratification system based on the colon cancer invasion-related genes, and evaluated the stability and accuracy of the model." (PMID 33579281, 2021). "We found that the expression levels of some genes enriched in IL-11+ fibroblasts, including Wnt5a, Mmp13, Timp1, Il1rl1, Cxcl5, Saa3, Inhiba, Ascl4, and Tnfrsf11b, were elevated in mouse AOM/DSS-induced colon tumor tissues." (PMID 33863879, 2021). "qRT–PCR assays showed that the mRNA expression levels of TIMP1 and BDNF were significantly higher in colon cancer cells than in NCM460 cells." (PMID 35003085, 2021). "Based on the earlier conducted functional enrichment analysis, we noticed that TIMP1, PF4 and SERPINA1 share a role in platelet degranulation, suggesting a key role for this biological process in colon cancer survival." (PMID 35008327, 2021). "Low expression of TIMP1 decreased the invasion and migration of SW480 and HCT116 colon cancer cells." (PMID 35003085, 2021). "We aimed to investigate the relationship of expression of matrix metalloproteinase-7 (MMP-7), tissue inhibitor of metalloproteinase-1 (TIMP-1) and cyclooxygenase-2 (COX-2) in colon cancer and its predecessor colon polyp." (PMID 29201696, 2015). "Our results showed that increased expression of TIMP-1 promotes in vivo growth of human HCT116 and HT-29 colon cancer cells." (PMID 24143225, 2013). "Here, we show that stroma of human prostate and colon cancer express higher levels of TIMP-1 compared to their normal counterparts and increased expression of TIMP-1 promotes in vivo growth of both cancer types." (PMID 24143225, 2013). "Here we show that stroma of human prostate and colon cancer express higher levels of TIMP-1 compared to their normal counterparts and that increased expression of TIMP-1 promotes in vivo growth of both cancer types." (PMID 24143225, 2013). "The effect of IL-1β and IP6 on the expression of mRNA of MMP-1, MMP-2, MMP-3, MMP-9, MMP-10, and MMP-13 and that of their tissue inhibitors TIMP-1 and TIMP-2 in colon cancer cells using real-time QRT-PCR assay was determined." (PMID 22415590, 2012). "Finally, we also detected the expression of FN1, TIMP1, and RAP1B in ex vivo by establishing the patient‐derived tumour‐like cell clusters (PTCs) from primary and metastatic colon cancer tumour tissues." (PMID 40638546, 2025). "This suggests that the abnormal expressions of AURKA, TIMP1, and NOX4 may play more pivotal roles in modulating the immune landscape during the oncogenesis and progression of colon cancer." (PMID 40290432, 2025). "In addition, results show a significant positive correlation between CCL3, MMP3, and TIMP1 expression and different immune cell types including dendritic cells, macrophages, CD8+ T cells, and neutrophils in patients with colon cancer." (PMID 36742294, 2023). "The diagnostic and prognostic value and potential mechanism of individual TIMPs were illustrated in various cancer types such as TIMP1 in gastric cancer for prediction 6, TIMP1 and TIMP2 in colon cancer for prognosis 7, 8 and TIMP4 in astrocytoma for diagnosis." (PMID 34093812, 2021). "In previously published results, we have shown that MMP-9 is upregulated in peripheral blood NK cells of colon cancer patients and the TIMP-1/MMP-9 axis, as well as uPAR, are altered, as compared to normal circulating NK cells." (PMID 33569050, 2020). "Previous studies revealed that TIMP-1 inhibited a disintegrin and metalloprotease (ADAM)-10 activity, which regulates cancer stem-like cells and tumor growth through activation of Notch signaling in colon cancer." (PMID 30486830, 2018). "In that study, MMP-9 and TIMP-1 also correlated with tumor stage, but no data were presented on survival nor, in contrast with our results, did patients with colon cancer have higher levels of MMP-9 than did rectal cancer patients." (PMID 29929486, 2018).
colon carcinoma (continued). "Western blot revealed that the protein levels of TIMP1 were differentially upregulated in all 4 colon cancer samples compared to the matched adjacent non-tumor tissues." (PMID 27644693, 2016). "To confirm the effect of TIMP-1 on CAFs, we performed similar IHC analyses on the tumor sections derived from the in vivo studies of HCT116 colon cancers with or without increased expression of TIMP-1." (PMID 24143225, 2013). "A significant overlap was detected with several relevant gene families, including colon cancer progression (e.g., FN1, IGBP3, PLAUR and TIMP1; P=0.00052), tumour cell apoptosis (e.g., BID, TNFRSF21, PHLDA1 and NOTCH1; P=1.46 × 10–6) and cell proliferation (e.g., CTGF, SPP1, FOLR1 and SPARC)." (PMID 21119668, 2010). "The second drug, shikonin, was reported to induce apoptosis and autophagy in colon cancer cells by targeting galectin-1 and the JNK-signaling pathway; however, its effect on TIMP1 has not been tested." (PMID 36146640, 2022). "Knockdown TIMP1 could inhibit the proliferation of colon cancer cell line by regulating FAK-PI3K/AKT and MAPK pathway, however we have not found the relationship between TIMP1 expression and patients' outcomes." (PMID 34093812, 2021). "Treatment with recombinant TIMP-1 or TIMP-2 showed a trend, although not statistically significant, to decrease CD49a+ and TIM-3+ expression and increase NKG2D in peripheral blood NK cells exposed to conditioned media from colon cancer cell lines." (PMID 34638439, 2021).
pulmonary fibrosis (84 papers, 2005 to 2025). Chronic progressive interstitial lung disorder characterized by the replacement of the lung tissue by connective tissue, leading to progressive dyspnea, respiratory failure, or right heart failure. "It was reported that dysfunction of collagen digestion enzymes (MMP2 and MMP8), and TIMP1 (a collagenase inhibitor) were associated with pulmonary fibrosis." (PMID 36717804, 2023). "In lung-associated fibrosis, ATP and uric acid are recognized by NLRP3, causing the recruitment of inflammatory cells IL-1 and TIMP1, worsening inflammation and promoting extracellular collagen synthesis, leading to pulmonary fibrosis." (PMID 36110858, 2022). "We measured TIMP1 as one of the main metallopeptidase inhibitors associated to lung fibrosis, TIMP1 expression augmented in the lung tissue after sepsis and it was successfully reduced in the CLP + MTX group." (PMID 34502521, 2021). "In other words, bleomycin-induced pulmonary fibrosis on 28th day was associated with a significant decrease in MMP-9/TIMP-1 ratio, signifying decrease in MMP-9 activity and increase in TIMP-1 activity." (PMID 32440328, 2020). "We have previously showed that batimastat significantly limits the development of bleomycin-induced pulmonary fibrosis in mice associated with a reduction of levels of TIMP-1." (PMID 27247426, 2016). "Bleomycin-induced pulmonary fibrosis, for example, causes the expression of significant levels of TIMP-1." (PMID 15663794, 2005). "Notably, cytokines associated with pulmonary fibrosis (i.e. TIMP-1, GM-CSF), profibrotic chemokines (i.e. MCP-1, MIP-1α, MIP-1β, TARC, MDC, KC), and anti-fibrotic chemokines (i.e. MIG, IP-10) were upregulated by cSiO2 exposure at both timepoints." (PMID 39418113, 2024). "Additionally, TIMP-1 has been reported to be strongly associated with radiation-induced lung fibrosis by the induction of macrophage and neutrophil infiltration in lung tissue." (PMID 37894899, 2023). "Upregulation of TIMP-1 expression has been reported to be associated with liver and lung fibrosis." (PMID 37063869, 2023). "Similarly, genes associated with ECM production and remodeling were significantly decreased with the loss of IL-31RA; these genes included MMP13 and TIMP1, as well as IL-6 which increased in wildtype mice during bleomycin-induced pulmonary fibrosis." (PMID 33815402, 2021). "Furthermore, it has been reported that high expression of TIMP1 is associated with liver and pulmonary fibrosis in animal models." (PMID 33022979, 2020). "Excessive TIMP-1 is also associated with fibrotic change, such as pulmonary fibrosis." (PMID 24278261, 2013). "Hence, TIMP-1 has been increasingly associated with pulmonary fibrosis." (PMID 16504062, 2006). "We demonstrated that miR-26 KO enhances PTEN expression and decreases downstream TIMP-1 expression, thereby attenuating pulmonary fibrosis in miR-26a KO mice." (PMID 41323794, 2025). "The results of this study showed that MMP9 and TIMP1 expression were upregulated in the lung tissues of rats with BLM-induced pulmonary fibrosis." (PMID 40438789, 2025). "In this study, EPM administration suppressed fibrosis-related markers, including TGF-β1, p-Smad3, Collagen III, α-SMA, and MMP-9, while upregulating antifibrotic mediators such as TIMP-1, thereby reducing the MMP-9/TIMP-1 ratio and mitigating lung fibrosis." (PMID 40507891, 2025). "Regarding TIMP-1 and pulmonary fibrosis, increased Timp1 mRNA and protein levels have been reported in the lung tissue and BALF following intratracheal BLM administration in C57BL/6 mice." (PMID 41323794, 2025). "This study by Nakashima and colleagues reveals that systemic miR-26a deficiency reduces pulmonary fibrosis by upregulating PTEN, thereby suppressing TIMP-1 in the PI3K/Akt-mTOR pathway." (PMID 41323794, 2025). "Several studies have demonstrated that increased expression of TIMP-1 plays a critical role in the development of experimental lung fibrosis." (PMID 39596365, 2024).
pulmonary fibrosis (continued). "MMPs/TIMPs are the main enzyme system regulating ECM degradation, and an imbalance between MMP-2 and TIMP-1 expression is a key link in the onset and progression of pulmonary fibrosis." (PMID 39770545, 2024). "Extracellular matrix protein TIMP-1 is another factor in regulating the progression of lung fibrosis." (PMID 39513364, 2024). "We identified over 2,500 O-GlcNAc modified proteins including α-SMA, TIMP1, TIMP3, Smad4, Smad5 and Smad3 have been implicated in pulmonary fibrosis." (PMID 38665916, 2024). "Early altered regulation of TIMP1 following bleomycin administration has been reported in bleomycin-induced pulmonary fibrosis." (PMID 38534359, 2024). "This study showed that SIN inhibited the abnormal expression of TIMP-1 and MMP-2/9 caused by pulmonary fibrosis and improved the physiological homeostasis of ECM." (PMID 38730387, 2024). "It has been reported that downregulation of TIMP-1 and reduced lung fibrosis in mice can result from neutrophil depletion during the inflammatory phase of the bleomycin injury model." (PMID 39513364, 2024). "The levels of lung fibrosis markers, including Timp1, collagen type I alpha 1 chain (Col1a1), and alpha-smooth muscle actin (α-SMA) mRNAs, were highest in bleomycin-treated alcohol-fed mice." (PMID 37457733, 2023). "Despite equal increases in type I collagen gene expression as in wild-type mice, TNF receptor null animals had lessened pulmonary fibrosis, which was accompanied by a diminished induction of tissue inhibitor of metalloproteinase-1 (TIMP-1) mRNA." (PMID 36835428, 2023). "All these factors point to the prospects for Timp1 silencing as an approach to therapy of not only acute inflammatory changes in the lung tissue but also their long-term effects, such as pulmonary fibrosis, which is the goal of our further investigations." (PMID 36675165, 2023). "MMP-9 has been found to be involved in the process of pulmonary fibrosis, and TIMP-1 is a specific inhibitor of MMP-9." (PMID 35402615, 2022). "The CytoHubba plug-in was then used to filter the top 10 nodes of the hub genes such as MMP-9 and TIMP-1, which are the common genes involved in pulmonary fibrosis." (PMID 35402615, 2022). "Our data agrees with a study in human lung fibrosis, where TIMP1 mRNA was markedly increased in response to lung injury, whereas there was no change in TIMP2 mRNA levels." (PMID 36032279, 2022). "This study therefore reveals that TIMP1 is a pro-fibrotic factor in CNT-induced lung fibrosis in mice." (PMID 32185174, 2020). "It has been demonstrated that MWCNT-induced lung fibrosis in mice corresponded with highly upregulated TIMP1 at both the mRNA and protein level in lung tissue." (PMID 33022979, 2020). "TIMP1 has been found to be increased transcriptionally and translationally in a mouse model of bleomycin-induced lung fibrosis." (PMID 31765403, 2019). "Still, in pulmonary fibrosis there is an increased expression of TIMP-1, suggesting an important regulatory role for this protein in inflammatory and fibrotic responses." (PMID 30696858, 2019). "High serum TIMP-1 levels characterize certain fibrotic diseases, such as liver cirrhosis, lung fibrosis, and skin fibrosis." (PMID 29458433, 2018). "Increased expression of TGF-β1, MMP-12, TIMP-1, CTGF, and fibronectin have been associated with the development of pulmonary fibrosis." (PMID 30087305, 2018). "In our study, the increased expression of TIMP-1, CXCL1, MCP-1, MIP-2, and IL-1ra was strongly associated with RT-induced lung fibrosis through the induction of alternatively activated macrophages and neutrophils." (PMID 30347679, 2018). "It has also been previously demonstrated that pulmonary fibrosis is closely associated with the activation of NLRP3-inflammasome pathway, production of IL-1β and TIMP-1." (PMID 27247426, 2016).
pulmonary fibrosis (continued). "Although lots of cytokines were regulated independently of HBoV status, several cytokines associated with lung fibrosis and tumour development, e.g., EGF, VEGF, TARC (CCL17), TNF-α, TNF-β, TIMP-1, were clearly upregulated in the HBoV-positive cohort." (PMID 26807786, 2016). "Increased levels of OPN, PC-1 and TIMP-1 are noted in rodent lungs in bleomycin induced pulmonary fibrosis." (PMID 24915862, 2014). "The present study showed that MMP-12 -/- mice developed pulmonary fibrosis in a similar intensity to WT mice and the level of TIMP-1 protein and Timp-1 mRNA is similar in both strains." (PMID 16504062, 2006). "Additionally, pathways such as the TIMP1/CD63/integrin β1 axis and ERK signaling have been implicated in MWCNT-induced lung fibrosis." (PMID 40423481, 2025). "Early inhibition of MMP9 and TIMP1 in lung tissue and maintenance of balance between alveolar collagen synthesis and degradation are expected to become new strategies for the treatment of pulmonary fibrosis." (PMID 40438789, 2025). "Additionally, BAFF also promotes pulmonary interstitial fibrosis by acting as a potent inducer of TIMP-1, α-SMA, CCL2, and IL-6." (PMID 38637830, 2024). "Studies also indicate that TIMP‐1 involves in the pathogenesis of pulmonary fibrosis." (PMID 39267201, 2024). "Using Timpl knockout mice, the authors could show that TIMP1 is a mediator of MWCNT-induced lung fibrosis." (PMID 37206955, 2021). "Earlier studies have shown that the reduction in MMP-9/TIMP-1 ratio is important in promoting bleomycin-induced pulmonary fibrosis, which is well-supported by the results of present study showing decrease in MMP-9/TIMP-1 ratio during bleomycin-induced pulmonary fibrosis." (PMID 32440328, 2020). "TIMP-1 and -2 are highly induced during fibrosis in a number of animal models of lung fibrosis." (PMID 31511015, 2019). "Expression of fibrosis-related factors such as transforming growth factor beta (TGF-β1), matrix metalloproteinase 12 (MMP-12), tissue inhibitor of metalloproteinases-1 (TIMP-1), connective tissue growth factor (CTGF), and fibronectin, have been associated with the development of lung fibrosis." (PMID 30087305, 2018). "MMP‐9 and TIMP‐1 play an important role in the development of pulmonary fibrosis." (PMID 26660549, 2015). "Two studies evaluating induction of kidney fibrosis by either UUO or protein overload show that the loss of TIMP-1 does not affect disease severity, similar to the lack of an effect on lung fibrosis but in contrast to its anti-fibrotic role in liver." (PMID 24713275, 2014). "According to our results, MMP-12 deficiency does not seem to be involved in TIMP-1 regulation and this would be consistent with the development of pulmonary fibrosis in MMP-12 -/- mice." (PMID 16504062, 2006). "The results showed that the salidroside could up-regulate TIMP-1 and reduce the expression of MMP-2, and the degree of lung tissue lesions, suggesting that the salidroside could inhibit the process of pulmonary fibrosis by regulating the balance of MMP-2/TIMP-1." (PMID 39770545, 2024). "Accordingly, it is proposed that NAC may inhibit bleomycin-induced development of pulmonary fibrosis by increasing the MMP-9/TIMP-1 and MMP-9/TIMP-3 ratios, which eventually increases the degradation of collagen in the lungs to prevent its excessive deposition in the form of fibrosis." (PMID 32440328, 2020). "Coincidently, two NF-κB-regulated genes encoding pro-fibrotic mediators, TIMP1 and OPN, are evidently induced in fibroblasts and myofibroblasts in MWCNT-exposed lungs, which confirms the transactivation of NF-κB and indicates the pro-fibrotic function of NF-κB in MWCNT-induced lung fibrosis." (PMID 32185174, 2020). "Rapamycin likely alleviates the progression of sepsis-induced pulmonary fibrosis by downregulating the expression of TGF-β1, α-SMA, MMP-2, and TIMP-1, thus protecting the lung." (PMID 40332776, 2025).